USP17L8 (ubiquitin specific peptidase 17 like family member 8)
Tractability: No criterion of Open Targets' tractability assessment is met for any kind of drug.
Gene: Protein-coding gene on chromosome 8 (7,971,661 to 7,973,253, reverse strand). Ensembl gene ENSG00000237038.
Subcellular location: Nucleus; Endoplasmic reticulum
Pathways (Reactome):
Metabolism of proteins: Ub-specific processing proteases
Gene Ontology:
Molecular function: cysteine-type deubiquitinase activity
Biological process: regulation of apoptotic process; protein deubiquitination
Cellular component: endoplasmic reticulum; nucleus
Homologues: Paralogues in human: USP17L4 (98% identical), USP17L2 (96% identical), USP17L3 (95% identical), USP17L1 (95% identical), USP17L17 (94% identical), USP17L11 (94% identical), USP17L20 (94% identical), USP17L22 (94% identical), USP17L18 (94% identical), USP17L24 (94% identical), USP17L25 (94% identical), USP17L26 (94% identical), and 59 more.